LRRC4 (leucine rich repeat containing 4)
Description:
Synaptic adhesion protein. Regulates the formation of exitatory synapses through the recruitment of pre-and-postsynaptic proteins. Organize the lamina/pathway-specific differentiation of dendrites. Plays an important role for auditory synaptic responses. Involved in the suppression of glioma (By similarity).
Synonyms: NGL-2; NAG14
Tractability: Small molecule: it belongs to a druggable protein family. Antibody: UniProt places it where antibodies can reach, with medium confidence; UniProt predicts a signal peptide or a membrane-spanning region; its Gene Ontology location is reachable by antibodies, with medium confidence.
Gene: Protein-coding gene on chromosome 7 (128,027,071 to 128,032,128, reverse strand). Ensembl gene ENSG00000128594.
Subcellular location: Membrane; Postsynaptic cell membrane
Subcellular location (Human Protein Atlas): Golgi apparatus
Gene Ontology:
Molecular function: protein binding; cell-cell adhesion mediator activity
Biological process: excitatory synapse assembly; modulation of chemical synaptic transmission; postsynaptic density protein 95 clustering; synaptic membrane adhesion
Cellular component: Golgi apparatus; glutamatergic synapse; plasma membrane; postsynaptic density membrane; membrane; postsynaptic membrane
Genetic constraint (gnomAD): Loss-of-function variants: 11 observed, 39.71 expected, observed/expected ratio (o/e) 0.28, 90% interval 0.17 to 0.46. The upper end of that interval is the gene's LOEUF score, 0.46, which puts it in group 2 of 6, group 1 being the genes least tolerant of losing a copy. Missense variants: 717 observed, 889.69 expected, observed/expected ratio (o/e) 0.81, 90% interval 0.76 to 0.86. Synonymous variants: 404 observed, 366.73 expected, observed/expected ratio (o/e) 1.1, 90% interval 1.01 to 1.2.
Homologues: Orthologues: macaque LRRC4 (99% identical), guinea pig LRRC4 (99% identical), dog LRRC4 (99% identical), pig LRRC4 (98% identical), mouse Lrrc4 (98% identical), chimpanzee LRRC4 (91% identical), rat Lrrc4 (89% identical), tropical clawed frog LRRC4 (85% identical), rabbit LRRC4 (77% identical), zebrafish lrrc4.2 (72% identical), zebrafish lrrc4.1 (71% identical). Paralogues in human: LRRC4B (55% identical), LRRC4C (54% identical), FLRT1 (19% identical), FLRT2 (19% identical), FLRT3 (19% identical), RTN4R (17% identical), LRRC15 (17% identical), LRRTM4 (16% identical), LRRTM3 (15% identical), NYX (15% identical), LRRC66 (15% identical), RTN4RL2 (15% identical), and 10 more.
Diseases named in the same sentence as LRRC4 in open-access papers:
LRRC4 is named in the same sentence as 41 diseases in open-access papers, as found by Europe PMC text mining. Sharing a sentence is not in itself a finding about the gene and the disease. The quoted sentences say what the papers report.
glioma (22 papers, 2008 to 2024). A benign or malignant brain and spinal cord tumor that arises from glial cells (astrocytes, oligodendrocytes, ependymal cells). "Taken together, these data indicated that LRRC4 was inversely associated with autophagy signalling and glioma patient outcomes." (PMID 32372061, 2020). "In glioma, miR-381 increased the proliferation of tumor cells by targeting LRRC4 and this action is associated with inducing MEK/ERK and AKT signaling." (PMID 28193228, 2017). "Promoter hypermethylation and miRNA dysregulation (miR-182, miR-381, and miR-185) have been identified as mechanisms underlying LRRC4 inactivation in glioma." (PMID 27884160, 2016). "Inactivated LRRC4 has been clinically detected in gliomas, and promoter hypermethylation has been implicated as the mechanism of inactivation in some of those tumors." (PMID 24404152, 2014). "In order to demonstrate a functional association between LRRC4 promoter methylation and its gene inactivation, we performed DNA demethylation analysis with two human glioma cell lines using methylation-specific PCR and RT-PCR." (PMID 18976507, 2008). "This lack of findings led us to explore an alternative mechanism underlying inactivation of LRRC4 in glioma." (PMID 18976507, 2008). "Importantly, in clinical glioma samples, LRRC4 was also negatively associated with DEPTOR and LC3 expression." (PMID 32372061, 2020). "LRRC4/NGL-2 also has the ability to form multiphase loops with miRNA, transcription factors and gene methylation modification; the loss of LRRC4/NGL-2 function may be an important event in multiple biological processes in gliomas." (PMID 25526788, 2014). "However, little is known about the mechanism of LRRC4 expression loss or down- regulation in glioma cell lines and biopsies." (PMID 18976507, 2008). "Based on these data, we speculated that the absence or down-regulation of LRRC4 expression in glioma may be caused by the 5' upstream regulatory sequence." (PMID 18976507, 2008). "Cluster profiler package was used to analyze these data, and result from KEGG pathway analysis showed that the differentially regulated genes participate in lysosomal function and drug metabolism, suggesting that LRRC4 may be associated with autophagy signalling and drug resistance in glioma." (PMID 32372061, 2020). "The loss of LRRC4 function hence may play important role in the biological processes of gliomas." (PMID 27612424, 2016). "Therefore, the loss of LRRC4/NGL-2 function may be an important event in multiple biological processes related to gliomas." (PMID 25526788, 2014). "Therefore, the loss of LRRC4 function may be an important event in the progression of gliomas and may act as a novel candidate for tumor suppression." (PMID 18976507, 2008). "In the glioma, LRRC4, an onco-suppressive gene, inhibited CXCR4-induced cell invasiveness by reducing ERK1/2 and Akt signaling." (PMID 36103228, 2022). "Meanwhile, one of its paralogs LRRC4 has been shown to have a putative tumor suppressor role in glioma by modulating the extracellular signal-regulated kinase/protein kinase B/nuclear factor-κB pathway." (PMID 34313788, 2021). "Our previous studies showed that LRRC4 regulates cytokine-induced NF-κB activation in glioma cells and that LRRC4 regulates the ERK/MAPK and the PI3K/AKT signaling pathway and therefore modulates cell proliferation, migration, and invasion." (PMID 33932995, 2021). "To investigate the new function of LRRC4 in glioma, we used RNA sequencing to analyse the differences in gene expression between LRRC4 stable ectopic expression and control U251 cell lines." (PMID 32372061, 2020). "In kidney cancer cells, LRRC4 was under-expressed, and identified as a tumor suppressor gene for gliomas." (PMID 33344459, 2020). "LRRC4 (Leucine-rich repeat-containing protein 4) is a transmembrane and cytoplasmic protein and plays an important role in neural development and malignant transformation of glioma." (PMID 32117780, 2020).
glioma (continued). "The expression of LRRC4, which is targeted by both miR-381 and miR-182, is decreased in glioma cells." (PMID 33324542, 2020). "The LRRC4 gene was first identified on human chromosome 7q31-32 by our group, and our reports confirmed that LRRC4 is a tumour suppressor gene for glioma." (PMID 32372061, 2020). "In conclusion, our results demonstrate that LRRC4, which is frequently deregulated in glioma, directly binds to DEPTOR and induces its degradation to activate mTOR, thereby inhibiting cell autophagy." (PMID 32372061, 2020). "Our group have confirmed LRRC4 as a tumour suppressor for glioma by inhibiting GBM cell proliferation and invasion." (PMID 32372061, 2020). "Homo sapiens leucine rich repeat containing 4 (LRRC4) is epigenetically inactivated commonly in glioma." (PMID 27670291, 2016). "Our studies indicated that LRRC4 is specifically expressed in brain tissue and decreases in primary brain tumor biopsies, especially in gliomas (up to 87.5%)." (PMID 27884160, 2016). "We also showed that miR-381 targets the LRRC4 gene, a known tumor suppressor of glioma, that overexpression of LRRC4 downregulates the expression of miR-381, and that the interaction between miR-381 and LRRC4 is involved in glioma growth." (PMID 25605243, 2015). "The precise roles of miR-182 and miR-381 in relation to LRRC4 expression in gliomas were investigated by the miRNA silencing tool of locked nucleic acids." (PMID 24404152, 2014). "LRRC4 is specifically expressed in normal brain tissues and is down-regulated or deleted in primary brain tumor biopsies (up to 87.5% in gliomas) and glioma cell lines." (PMID 24404152, 2014). "LRRC4/NGL-2 suppressed glioma cell proliferation by delaying the cell cycle in late G1 and did not induce apoptosis of tumor cells." (PMID 25526788, 2014). "In the current study, LNA-mediated miR-182 and miR-381 silencing was applied and found to restore the expression of LRRC4 in gliomas." (PMID 24404152, 2014). "We further found that the expression of miR-182 and miR-381 or BRD7 and LRRC4 were negatively correlated with the pathological progression of gliomas." (PMID 24404152, 2014). "When the glioma-related LRRC4 gene was queried by TargetScan and PicTar software, it was identified as a target gene of miR-182 and miR-381." (PMID 24404152, 2014). "Previous studies have demonstrated that LRRC4, a regulator of miR-182 and miR-381, can inhibit glioma tumorigenicity by modulating receptor tyrosine kinase (RTK) signaling pathways, such as the K-Ras/p-c-Raf/ERK/MAPK and PI-3K/AKT signaling pathways." (PMID 24404152, 2014). "Our previous researches indicated that LRRC4 is a target gene of miR-381, the interaction of miR-381 and LRRC4 is involved in glioma growth." (PMID 24404152, 2014). "To evaluate the relevance of the endogenous expressions of miR-182, miR-381, BRD7, and LRRC4, we assessed their expressions in human glioma tissues, as well as in normal brain tissues." (PMID 24404152, 2014). "LRRC4 has been characterized as a tumor suppressor gene involved in glioma formation, and our previous study indicated that LRRC4 is a target of miR-381." (PMID 24404152, 2014). "The other dysregulation mechanisms of LRRC4/NGL-2 in glioma result from the miRNA-dependent regulatory network." (PMID 25526788, 2014). "Together, these findings demonstrated that LRRC4/NGL-2 can be identified as a tumor suppressor gene in the tumorigenesis of glioma." (PMID 25526788, 2014). "LRRC4/NGL-2 significantly inhibited glioma cell proliferation and greatly reduced its capacity to form colonies." (PMID 25526788, 2014). "The results from studies on LRRC4/NGL-2 suggest that LRRC4/NGL-2 is not only a brain-specific gene, but it has been identified as a tumor suppressor gene for gliomas." (PMID 25526788, 2014).
glioma (continued). "The overexpression of LRRC4/NGL-2 suppresses glioma cell growth, angiogenesis and invasion through complicated signaling regulation networks." (PMID 25526788, 2014). "LRRC4/NGL-2 overexpression inhibited glioma cell growth and invasion through miR-185-mediated CDC42 and RhoA direct regulation and VEGFA indirect regulation." (PMID 25526788, 2014). "Previous studies had indicated that LRRC4 was down-regulated in glioma biopsies and cell lines, and that methylation of the LRRC4 promoter was one of the reasons for LRRC4 inactivation in some gliomas." (PMID 24404152, 2014). "LRRC4/NGL-2 is a target gene of miR-381 and miR182; meanwhile, the overexpression of LRRC4/NGL-2 downregulated the expression of miR-381 and miR182 in glioma cells." (PMID 25526788, 2014). "The study not only demonstrated the mechanism of tumor suppressor gene LRRC4 involved in the glioma progression, but also provided the therapy targets for glioma." (PMID 24404152, 2014). "We found that the expressions of miR-182, miR-381 or BRD7 proteins were inversely correlated with expression of LRRC4 in glioma tissues and normal brain tissues." (PMID 24404152, 2014). "It was demonstrated that the LRRC4-AP-2-miR-182-LRRC4 loop formed among LRRC4/NGL-2, miR-182 and AP-2 was involved in glioma development." (PMID 25526788, 2014). "Taken together, these findings suggest that promoter methylation is an important mechanism in the inactivation of LRRC4 in glioma." (PMID 18976507, 2008). "The present study implies that methylation-mediated inactivation of LRRC4 is involved in the initiation and development of glioma." (PMID 18976507, 2008). "To determine a more detailed map of the methylation in the LRRC4 promoter, we performed bisulfite sequencing around the promoter region of the LRRC4 gene in some of the glioma biopsies and cell lines studied above." (PMID 18976507, 2008). "We next evaluated the relationship between expression of LRRC4 and glioma survival rate." (PMID 32372061, 2020). "Moreover, autophagy inhibition increased the treatment efficacy of TMZ in glioma, and LRRC4-expressing cells underwent increased apoptosis with TMZ treatment." (PMID 32372061, 2020). "Previous studies have confirmed that LRRC4 plays a central role in early nervous system development and differentiation, especially during synapse formation; in addition, our group first confirmed a new function of LRRC4 as a tumour suppressor for glioma." (PMID 32372061, 2020). "Although the function of LRRC4 has been reported in our previous work, it is unknown whether LRRC4 may mediate autophagy in glioma." (PMID 32372061, 2020). "The interaction of hsa-miR-381 with LRRC4 is involved in the pathogenesis of glioma and could be a potential therapeutic target." (PMID 33324542, 2020). "In addition, the overexpression of LRRC4 suppresses glioma cell growth, angiogenesis and invasion through complicated signaling regulation networks." (PMID 27612424, 2016). "Thus, it was suggested that LNA-mediated miR-182 and miR-381 silencing down-regulated the expression of BRD7 by restoring LRRC4 expression in gliomas." (PMID 24404152, 2014). "Furthermore, LRRC4/NGL-2 inhibited the glioma tumor cell invasion through regulating the expression of the invasion-related molecules including CD44, MMP16, TB10 and annexin A2." (PMID 25526788, 2014). "Methylation of LRRC4 was detected in both the early and late stages of glioma, indicating that the inactivation of the LRRC4 gene might be essential in the early development of glioma and persist through the course of development." (PMID 18976507, 2008).
glioma (continued). "Treatment of SF126 and SF767 cells with 5-Aza-dC restored LRRC4 expression, which suggests that aberrant hypermethylation of the promoter is directly responsible for transcription inactivation of its expression in glioma cell lines." (PMID 18976507, 2008). "LRRC4 inactivation is commonly found in glioma cell lines and primary glioma biopsies." (PMID 18976507, 2008). "Our previous study indicated that LRRC4 may be an adhesive protein or/and receptor, and it inhibited glioma invasion and metastasis." (PMID 18976507, 2008). "Since the ability of invasion and metastasis is closely related to prognosis in glioma, LRRC4 methylation may also be a biomarker for prognosis." (PMID 18976507, 2008). "Methylation-mediated inactivation of LRRC4 is a frequent and glioma-specific event, and it may be a potential biomarker for diagnosis or prognosis, or serve as a therapeutic target." (PMID 18976507, 2008). "To investigate whether aberrant methylation of the LRRC4 in glioma cell lines reflects an epigenetic event occurring in primary glioma, we next examined 30 primary glioma biopsies and three tissue specimens of normal brain for LRRC4 methylation." (PMID 18976507, 2008). "In addition, our findings demonstrate that methylase inhibitor can reverse LRRC4 expression in glioma, and it is possible to restore its function as tumor suppressor gene at some degree." (PMID 18976507, 2008). "In summary, methylation-mediated inactivation of LRRC4 is a frequent and glioma-specific event that may be a potential biomarker for diagnosis and prognosis, or a useful target for therapy." (PMID 18976507, 2008). "Moreover, overexpression of LRRC4 suppressed glioma cell growth, angiogenesis, and invasion." (PMID 33344459, 2020). "Also, through targeting LRRC4, miR-381 regulates glioma growth." (PMID 26688820, 2015). "Thus, the loss of LRRC4/NGL-2 function may directly contribute to the increasing tumor grade and is a late event in the pathogenesis of gliomas." (PMID 25526788, 2014). "Protective genetic changes in glioma include increased expression of ADGRB3/1, IL12B, DYRKA1, VEGFC, LRRC4, and BMP4." (PMID 39022728, 2024). "LRRC4 is a proposed TSG involved in nervous system development and differentiation, and was reported to be hypermethylated and downregulated in gliomas." (PMID 28052017, 2017). "Our results demonstrated that the D domain of LRRC4 anchors ERK1/2 in the cytoplasm and competitively inhibits MEK/ERK activation in glioma cells." (PMID 27884160, 2016). "We previously found that Leucine-rich repeat containing 4 (LRRC4) was a tumor suppressor and a negative regulator of the ERK/MAPK pathway in glioma tumorigenesis." (PMID 27884160, 2016). "We also investigated the interaction of LRRC4 and ERK1/2 and the role of the D domain in ERK activation in glioma cells." (PMID 27884160, 2016). "Ectopic LRRC4 expression, 5-Aza-dC treatment, and BRD7-siRNA transfection each inhibited cell proliferation and induced cell cycle arrest at G0/G1 in glioma cells." (PMID 24404152, 2014). "LRRC4/NGL-2, a member of the LRR superfamily thought to be involved in tumorigenesis and the development of the nervous tissues, has the potential to suppress gliomas cell growth, angiogenesis and invasion through complex regulation networks." (PMID 25526788, 2014). "The methylation-mediated inactivation of LRRC4/NGL-2 was found to be a frequent and glioma-specific event." (PMID 25526788, 2014). "It was indicated that the LRRC4/NGL-2-miR-185-DNMT1-LRRC4/NGL-2 loop among LRRC4/NGL-2, miR185 and DNMT1 participated in glioma development." (PMID 25526788, 2014). "In previous researches, we had focused on the effect of LRRC4 on the ERK/MAPK and PI-3K/AKT signaling pathways in gliomas, and transcriptional regulation of BRD7 expression in NPCs." (PMID 24404152, 2014).